CLDN1 (claudin 1)
Diseases named in the same sentence as CLDN1 in open-access papers (continued):
Sharing a sentence is not in itself a finding about the gene and the disease.
NISCH syndrome (14 papers, 2013 to 2025). "Silencing of Cldn1 in hepatocytes increases paracellular permeability and has been linked to neonatal ichthyosis–sclerosing cholangitis (NISCH) syndrome." (PMID 40940777, 2025). "Pathogenic non- and missense mutations have been described for many claudins including CLDN1 (NISCH syndrome), −2 (obstructive azoospermia), −5 (alternating hemiplegia), −10 (HELIX syndrome), −14 (DFNB29 deafness), −16 and −19 (both FHHNC syndrome)." (PMID 37514167, 2023). "NISCH syndrome is a rare genetic disorder secondary to the CLDN1 variant that determines claudin-1 deficiency and affects hepatic tight junctions (TJs)." (PMID 37928553, 2023). "NISCH syndrome represents an extremely rare autosomal-recessive ichthyosis syndrome caused by mutations in the CLDN1 gene leading to its abolished expression in liver and skin (KO phenotype)." (PMID 32012812, 2020). "Complete loss of claudin-1 in human results in the neonatal ichthyosis sclerosing cholangitis (NISCH) syndrome." (PMID 32698388, 2020). "This is in line with a hair growth phenotype in claudin-1 deficient patients (NISCH syndrome) and corresponding knock-out mice and indicates an important role of claudin-1 in HF barrier function and growth." (PMID 30143655, 2018). "Claudin-1 mutations have been observed in the rare disease NISCH syndrome (ichthyosis and neonatal sclerosing cholangitis);." (PMID 23685254, 2013). "Claudin-1 is essential for skin barrier function, as evidenced by claudin-1 null mice, which die of dehydration soon after birth and claudin-1 mutations associated with the human disease neonatal ichthyosis-sclerosing cholangitis (NISCH) syndrome." (PMID 39000205, 2024). "Loss of Claudin 1 function mutations could result in neonatal ichthyosis-sclerosing cholangitis syndrome, while the gene mutations in CLDN16 could cause familial hypomagnesemia with hypercalciuria and nephrocalcinosis (FHHNC) which is a rare autosomal recessive renal disease." (PMID 29467824, 2018). "Molecular analyses identified CLDN1 (coding for claudin-1) defects, and the authors assigned a syndrome associating NSC and ichthyosis (#607626, NISCH syndrome)." (PMID 37296768, 2023). "On the other hand, CLDN1 mutations cause neonatal ichthyosis sclerosing cholangitis hypotrichosis (NISCH) syndrome, but pain is not described in these patients." (PMID 34576252, 2021). "CLDN1 and TJP2 encode integral TJ proteins; mutations in CLDN1 were found in neonatal ichthyosis-sclerosing cholangitis syndrome (NISCH) and TJP2 mutations cause familial hypercholanemia (FHC) and a newly described subtype of Progressive Familial Intrahepatic Cholestasis syndrome (PFIC-4)." (PMID 26116792, 2015). "Thus, increased paracellular permeability and secondary bile injury due to CLDN1 absence in patients with NISCH syndrome may be compensated by overexpression of other TJ protein members in the liver, explaining the variable phenotype." (PMID 32012812, 2020). "NISCH syndrome, a rare human genetic disease due to complete absence of claudin-1, is often accompanied by alopecia and reduced eyebrows/lashes (see Section 2.1.2)." (PMID 32698388, 2020).
diabetes (13 papers, 2010 to 2025). "Hyperglycemia is a main pathogenic factor of diabetes, and HG incubation increased claudin-1 and claudin-3 expression and reduced paracellular permeability in SMG-C6 cells." (PMID 34831451, 2021). "Conversely, diabetes-induced upregulation of claudin-1 in podocytes causes slit diaphragm-tight junction transition and consequently proteinuria." (PMID 30707256, 2019). "Since retinal vascular leakage is common to see in DR patients, the state of vascular leakage was measured in NPDR mice by determining the expressions of tight junction proteins, including occludin-1, claudin-1, and ZO-1 which are closely linked to vascular permeability in diabetes." (PMID 34699316, 2021). "The mRNA levels of ZO-1, occludin, and claudin-1 expressed in the intestine decreased in the DM group, indicating that diabetes induction with STZ destroyed the intestinal barrier function." (PMID 34692563, 2021). "Consistent with this notion, a “proximal tubule-podocyte communication” has been inferred by which tubular sirtuin-1 is able to downregulate claudin-1 expression in podocytes and thus afford protection against diabetes-induced albuminuria." (PMID 32604897, 2020). "Previous studies have reported lower levels of the major intercellular tight junction protein claudin-1 and greater intestinal permeability in the BB animal model before the onset of diabetes." (PMID 20463897, 2010). "We also measured CLDN1 protein level by immunostaining in IECs and found a pattern consistent with its mRNA level, indicating that STZ‐HSCT/STZ/↑Sod2 treatment reverses, while CTL‐HSCT/CTL/shSod2 treatment mimics, maternal diabetes–mediated CLDN1 suppression in IECs." (PMID 35220596, 2022). "During diabetes, inhibition of miR-22-3p increases claudin-1 and -3 expression by directly targeting Sp1, resulting in lower epithelial paracellular permeability in SMG epithelial cells, which might contribute to the dysfunction of the diabetic SMG." (PMID 34831451, 2021). "In addition, diabetes downregulated tight junction proteins (ZO-1, occludin, and claudin-1) and increased intestinal permeability to impair the intestinal barrier." (PMID 34084135, 2021). "Our present results showed decreased levels or decreased tendency of ZO-1, occludin, and claudin-1 in the DM group, indicative of disruption of the tight junction barrier under diabetes." (PMID 34692563, 2021). "We found that maternal diabetes induction (STZ‐HSCT/STZ/EMP) significantly decreased mRNA levels of Sod2, Zo1, and Cldn1, compared with the control (CTL‐HSCT/CTL/EMP) group." (PMID 35220596, 2022).
ichthyosis (13 papers, 2013 to 2025). Disorders of cornification that are characterized by visible scaling and/or hyperkeratosis of most or all of the skin. "Previous studies have demonstrated that CLDN1 mutation can cause ichthyosis-hypotrichosis-sclerosing-cholangitis (IHSC)." (PMID 36060137, 2022). "Impaired TJ function caused by LOF mutations in claudin-1 (CLDN1) causes ichthyosis and sclerosing cholangitis in humans, and CLDN1-knockout mice die postnatally from dehydration and develop AD-like features when the expression is systematically regulated." (PMID 35052551, 2021). "The patients with neonatal ichthyosis and sclerosing cholangitis syndrome have a premature stop codon mutation in CLDN1, resulting in a failure of mature CLDN1 protein, and present ichthyosis, a skin disorder." (PMID 32992650, 2020). "Claudin-1-deficient patients are known to suffer from neonatal ichthyosis-sclerosing cholangitis, a condition that manifests an ichthyosis skin phenotype." (PMID 27588419, 2016). "We propose that alterations in claudin-1 stability contributes to, or is responsible for, HAI-1 deficiency-induced ichthyosis." (PMID 32326212, 2020). "The Cldn1 downregulation induces skin inflammation and ichthyosis." (PMID 41515359, 2025). "For instance, a premature stop codon in CLDN1 has been identified in neonatal ichthyosis." (PMID 39637147, 2024). "A premature stop codon of CLDN1, resulting in a lack of CLDN1 protein, has been identified in neonatal ichthyosis and sclerosing cholangitis syndrome, a disorder characterized by scalp hypotrichosis, ichthyosis, scarring alopecia, and sclerosing cholangitis." (PMID 31398894, 2019).
Obesity (13 papers, 2016 to 2025). Accumulation of substantial excess body fat. "Obesity is closely linked to inflammation, as fat accumulation and localized inflammation reduce the expression of tight junction proteins (e.g., claudin-1, occludin, and ZO-1), thereby increasing intestinal permeability and triggering inflammation." (PMID 40535017, 2025). "According to this evidence, CLDN1 was revealed to be a target gene induced in the omental AT of humans living with obesity and is associated with inflammation and fibrosis in this depot." (PMID 40871639, 2025). "In a recent study published by our laboratory, we confirmed the high levels of CLDN1 in the VAT of patients living with obesity." (PMID 40871639, 2025). "Elevated expression of genes CLDN1, OCLN, and ZO1 encoding tight junction proteins to enhance intestinal permeability in obesity." (PMID 40129979, 2025). "In our study, CB 0313.1 significantly restored obesity-induced down-regulation of claudin-1 and occludin at both transcriptional and protein levels." (PMID 27123997, 2016). "This evidence suggests the possibility of common mechanisms being present in other organs, such as AT, where CLDN1 could have a specific role in the development of fibrosis in obesity." (PMID 40871639, 2025). "Moreover, CLDN1 was found to be specifically upregulated in VAT-infiltrated T cells from patients living with obesity, suggesting a role for CLDN1 in pathophysiological AT alterations during obesity." (PMID 40871639, 2025). "Supportive of an obesity-specific effect, depletion of either CLDN1 or LCN2 did not affect tumor take rate in the lean mice." (PMID 35013251, 2022).
Sepsis (13 papers, 2015 to 2026). Sepsis is defined as life-threatening organ dysfunction caused by a dysregulated host response to infection. "HIF-1a activation protected the intestinal mucosal barrier by reducing intestinal mucosal permeability and regulating Claudin-1, a TJ protein, and then alleviated the damage to the intestinal mucosal barrier caused by sepsis; while a HIF-1α inhibition had the opposite effects." (PMID 35576220, 2022). "Herein, we found that acute abdomen III lowered the endotoxin, D-lactate, and DAO levels in sepsis, and also enhanced the expressions of tight junction proteins (ZO-1, claudin-1, and occludin), which were crucial in maintaining intestinal epithelial integrity." (PMID 40582762, 2025). "In summary, acute abdomen III reduced sepsis-induced inflammation, thereby promoting the levels of ZO-1, claudin-1 and occludin, which implied its role in protecting intestinal barrier function." (PMID 40582762, 2025). "While the role of such combined approaches in thyroid cancer remains unexplored, atezolizumab (an anti-PD-L1 agent) increased the expressions of claudin-1 and occludin in murine ileum during sepsis." (PMID 39458944, 2024). "Compared with that in the sham group, the expression level of HIF-1α was significantly increased in the sepsis group (P < 0.05), and the expression levels of ZO-1, occludin and claudin-1 were significantly decreased (P < 0.05)." (PMID 35576220, 2022). "Our findings supported observations of disruption of tight-junction proteins during conditions like sepsis, where it was reported that intestinal permeability resulted from disruption of the tight-junction structure (claudin 1,3,4,5 and 8) in mice models." (PMID 35292710, 2022). "Further analysis showed that ZO-1 and Claudin-1 were reduced in the ileum by sepsis but enhanced by SST." (PMID 33376482, 2020). "Western blot analysis showed that sepsis-induced reduction of ZO-1 and Claudin-1 in the ileum was blocked by SST or/and JSH-23 (P < 0.05)." (PMID 33376482, 2020). "In our research, ZO-1 and Claudin-1 were reduced in the sepsis mouse while their expressions were promoted by SST treatment." (PMID 33376482, 2020). "Although our model for sepsis was different as we used IP injections of LPS to induce sepsis, our results are similar to other studies cited above as there was a notable decrease in claudin-1 and occludin expression in BF mice." (PMID 31790417, 2019). "The mRNA-levels of different cell adhesion proteins were all numerically upregulated during sepsis, with a significant peak in claudin-1, desmoglein-2 and E-cadherin mRNA levels." (PMID 27044016, 2016). "The mRNA-levels of claudin-1, occludin and E-cadherin were significantly higher during sepsis, and septic animals curatively treated with anti-IL-6 did not display this increase in mRNA levels." (PMID 27044016, 2016). "Additionally, DYY inhibited inflammation (TNF-α, IL-1β, and IL-6), cell apoptosis, and promoted proliferation in sepsis, as well as the promotion of tight junction proteins (claudin-1, occludin, and ZO-1)." (PMID 41948377, 2026). "Importantly, IAP influences the expression of TJ proteins, and has specifically been shown to upregulate claudin-1 mRNA levels in a mouse model of sepsis." (PMID 38201850, 2023). "In this study, the expression of the TJ proteins ZO-1, occludin and claudin-1 in the intestinal mucosa was decreased in septic rats, and the pathological morphology of the intestinal mucosa was destroyed, suggesting that sepsis leads to the destruction of the morphology of intestinal mucosa." (PMID 35576220, 2022). "The result indicated that ZO-1 and Claudin-1 were reduced in mice with sepsis, while decrease of ZO-1 and Claudin-1 expressions could be reversed by SST treatment (P < 0.001)." (PMID 33376482, 2020). "In addition, GIK increased the expression of tight junction proteins, including ZO-1, occludin, and claudin-1, during sepsis and thus decreased the intestinal permeability." (PMID 28428961, 2017).
Sepsis (continued). "Compared with the sepsis group, the sepsis + DMOG group exhibited significantly higher expression levels of HIF-1α and ZO-1, occludin and Claudin-1 in the intestinal mucosa (P < 0.05) (P < 0.05)." (PMID 35576220, 2022). "We used the CLP manoeuvre to establish a murine model for sepsis-induced ALI and found that FA improved alveolar epithelial cell barrier function, as evidenced by the recovered expression of the tight junction proteins ZO-1, occludin and claudin-1." (PMID 36433644, 2022). "Furthermore, the expression level of HIF-1α was lower in the sepsis + BAY 87–2243 group (P < 0.05), and the protein expression levels of ZO-1, occludin and claudin-1 protein were significantly decreased (P < 0.05)." (PMID 35576220, 2022). "However, the noteworthy feature is the significant increase in the cecal expression of “sealing proteins,” claudin-1 and occludin, in HF diet mice as compared to BF diet mice, as this suggests that both proteins may potentially play a role in improving barrier function in sepsis." (PMID 31790417, 2019). "CORM-2, but not iCORM-2, significantly reduced sepsis-induced damage of intestinal mucosa (including TJ disruption), TJ protein reduction (including zonula occludens-l (ZO-1), claudin-1 and occludin), MLC phosphorylation and proinflammatory cytokine release." (PMID 26720630, 2015).
oral squamous cell carcinoma (12 papers, 2012 to 2025). "Specifically, the overexpression of claudin-1 and downregulation of claudins-4, -7, and -17 have been linked with poor survival in oral squamous cell carcinoma patients." (PMID 37686483, 2023). "Claudin-1 promotes the invasive ability of oral squamous cell carcinoma OSC-4 and NOS-2 cell lines through MT1-MMP and MMP-2 activation." (PMID 35280730, 2022). "Alarmingly, overexpression of claudin-1 is correlated with oral squamous cell carcinoma." (PMID 39996934, 2025). "IIn oral squamous cell carcinoma, ANLN knockdown increases expression of epithelial markers such as cadherin-1(CDH1) and claudin-1(CLDN1), while reducing mesenchymal markers including vimentin, SNAIL1, and SNAIL2, leading to attenuated EMT." (PMID 41573677, 2025). "In oral squamous cell carcinoma (OSCC), claudin-1 expression levels ranged from high to no change." (PMID 37686483, 2023).
liver cancer (11 papers, 2015 to 2025). An epithelial or non-epithelial malignant neoplasm that arises from the liver. "HCV is a major cause of liver cancer, and treatment of patient-derived cancer cells with monoclonal antibodies against claudin-1, the receptor for HCV, suppresses liver cancer growth in ex vivo models." (PMID 38712627, 2024). "Notably, alterations in CLDN1 expression have been identified as important biomarkers of tumor progression in various cancers, including breast, ovarian, and liver cancer." (PMID 41249135, 2025). "CLDN1 regulation of cell autophagy was also described in 5-FU resistant HepG2 (liver cancer) cells." (PMID 37041570, 2023). "Among those genes, CLDN1, ITGA6 and ID2 have been reported to promote EMT, cell migration and proliferation in liver cancer cells, and the resminostat/sorafenib drug combination reduced the mRNA level of these genes (significantly for CLDN1 p = 0.0008, ITGA6 p = 0.0009)." (PMID 33953226, 2021). "Because CLDN1-induced acquisition of the malignant EMT phenotype, it was exploited as a biomarker for metastasis in liver cancer." (PMID 25544763, 2015). "However, regulation of hepatic CLDN1 expression by microRNAs was not clearly investigated in HCV infection, but it was just investigated in liver cancer, showing that both miR-198 and miR-199a enhanced CLDN1 expression." (PMID 29616082, 2018).